IL1B (interleukin 1 beta)
Diseases named in the same sentence as IL1B in open-access papers (continued):
Sharing a sentence is not in itself a finding about the gene and the disease.
B cell deficiency (3 papers, 2019 to 2021). A broad classification of disorders where circulating numbers of B lymphocytes are decreased or ineffective. "B-cell deficiency did not affect expression of IL1β nor other DAM genes, such as TNFα, Igf1, and Lilrb4." (PMID 33846335, 2021).
babesiosis (3 papers, 2020 to 2025). Babesiosis refers to a condition caused by microscopic parasites that infect the red blood cells. "In babesiosis caused by B. bovis, the infection involves production of IL-1β, interleukin-12 (IL-12), gamma interferon (IFN-γ) and TNF-α." (PMID 33132601, 2020). "The response of PBMCs from adult cattle during the acute phase of the babesiosis at 10 dpi showed upregulation of the pro-inflammatory cytokines IL-1β, TNFα and IL-18." (PMID 41398915, 2025).
bronchiolitis (3 papers, 2017 to 2023). Inflammation of the bronchioles characterized by swelling of the bronchioles and mucus accumulation. "Measurements by NS demonstrated that relative to both RSV− bronchiolitis and healthy control subjects, RSV+ bronchiolitis was associated with higher levels of IFN-γ, IL-1β, CCL5/RANTES, and IL-10 (respectively) (P < .05 throughout)." (PMID 28368490, 2017). "Here we show that elevated levels of pro-inflammatory cytokines (IL1β, IL6, TNFα, IL18, IL23), regulatory cytokines (IL10, IL17A) and IFNγ were found in the three bronchiolitis cohorts." (PMID 36561744, 2022). "Pro-inflammatory cytokines IL1β, IL6, TNFα, IL18 and IL23 were increased in the bronchiolitis samples relative to their respective control cohort." (PMID 36561744, 2022).
Burkholderia Infections (3 papers, 2017 to 2021). Infections with bacteria of the genus BURKHOLDERIA. "We and others have previously shown that processing and secretion of the mature form of IL-1β and IL-18 in response to Burkholderia infection was dependent on caspase-1." (PMID 29791511, 2018). "Since Nramp1 is well-known to have pleiotropic effects on release of pro-inflammatory cytokines, including IL1-β, TNF-α and IL-6, in response to bacterial uptake, we also investigated the effects of Nramp1 on production of pro-inflammatory cytokines in response to Burkholderia infection." (PMID 28848712, 2017).
burn (3 papers, 2020 to 2024). A traumatic injury involving interruption of tissue cohesiveness that results from exposure to caustic chemicals, extreme heat, extreme cold or excessive radiation. "Burn injuries resulted in a markedly higher level of IL-1β and IL-6 production in the serum (P < 0.01)." (PMID 33985568, 2021). "Based on this result, we speculate that effectively inhibiting the expression of the NLRP3 inflammasome in the early stage of alkali corneal burns can inhibit IL-1β secretion and reduce the inflammatory response." (PMID 32322412, 2020). "Burn patients showed a decreased enrichment of H3K9me2 in CXCL8, IL-17, and TNFA promoters, whereas IL-6, FOS, and IL-1B promoters displayed an H3S28p enrichment diminution during the first 10 days post-burn." (PMID 39768289, 2024).
Buruli ulcer (3 papers, 2020 to 2022). "We found that, in the context of Buruli ulcer, the mycolactone produced by M. ulcerans or present in extracellular vesicles derived from this bacillus, induces IL-1β secretion by macrophages." (PMID 33338061, 2020). "We also detected IL-1β protein in a mouse model of M. ulcerans infection as well as in biopsies of Buruli ulcer patients." (PMID 33338061, 2020). "Finally, several soluble pro-inflammatory factors, including IL-1β, were detected in infected tissues from mice and Buruli ulcer patients." (PMID 33338061, 2020). "Finally, to demonstrate the secretion of IL-1β in the context of Buruli ulcer, we performed histological analyses on biopsy specimens from patients with PCR-confirmed disease." (PMID 33338061, 2020).
CADASIL (3 papers, 2023 to 2025). "Previous studies have detected systemic inflammatory cytokines, including IL-1β, IL-6, TNF-α, CCL2, and CXCL16, and found that their expression levels were significantly elevated in CADASIL patients, which is consistent with our results." (PMID 41000387, 2025). "The serum inflammatory cytokines were analyzed by ELISAs and revealed that the levels of serum IL-1β, IL-6, TNF-α, CCL2, and CXCL16 were significantly elevated in the patient group compared with their family members, suggesting a systemic inflammation in CADASIL patients." (PMID 37684694, 2023).
cervical (3 papers, 2017 to 2023). "Accordingly, the rs10754558 G allele may alter the function of NLRP3, thereby influencing IL-1β and IL-18 secretion in a manner that enhances inflammatory cascade activity and drives pathological changes conducive to cervical oncogenesis." (PMID 37885032, 2023). "Furthermore, increased cervical IL-1β, IL-6, and IL-8 were detected among HIV positive women with cervicitis." (PMID 35583346, 2022).
Chagas cardiomyopathy (3 papers, 2020 to 2024). A disease of the cardiac muscle developed subsequent to the initial protozoan infection by trypanosoma cruzi. "Interestingly, the CT haplotype for IL1B −31 T>C and +3,954 C>T was more prevalent in patients with Chagas cardiomyopathy in a Colombian population." (PMID 33193300, 2020). "The individuals with an indeterminate state had higher IL-10 expression, whereas the Chagas cardiomyopathy group presented the highest inflammatory cytokine expression (IFN-γ, TNF-α, IL-6 and IL-1β)." (PMID 38133693, 2023).
cholangiocarcinoma (3 papers, 2015 to 2023). A carcinoma that arises from the intrahepatic biliary tree (intrahepatic cholangiocarcinoma) or from the junction, or adjacent to the junction, of the right and left hepatic ducts (hilar cholangiocarcinoma). "In gastric and cholangiocarcinoma cell lines, proinflammatory cytokines including IL-1β, IL-6, and TNF-α have all been reported to induce Cdx2 gene expression." (PMID 26460825, 2015).
cholangitis (3 papers, 2021 to 2025). An acute or chronic inflammatory process affecting the biliary tract. "Based on changes in clinical indicators, we evaluated the effect of an IL-1β inhibitor and found that it effectively promoted endotoxin accumulation in adipose tissue and attenuated inflammatory marker levels in a rat model of cholangitis." (PMID 41438472, 2025). "It has been previously shown that expression of IL-8 in human biliary epithelial cells is stimulated by proinflammatory cytokines IL-1β and TNF-α, and lipopolysaccharide produced by gram negative bacteria, which are commonly causative microbes underlying BA associated cholangitis." (PMID 34207442, 2021).
cholelithiasis (3 papers, 2019 to 2024). The presence of crystallized deposits forming in the gallbladder or biliary tree, primarily composed of cholesterol, bilirubin, and bile. "In addition, the ELISA results showed that TNF-α, IL-1β, and IL-18 expression was markedly up-regulated in the gallbladder tissues of mice with cholelithiasis compared with the normal control mice." (PMID 37641009, 2023).
chronic bronchitis (3 papers, 2015 to 2024). A type of chronic obstructive pulmonary disease characterized by chronic inflammation in the bronchial tree that results in edema, mucus production, obstruction, and reduced airflow to and from the lung alveoli. "In this context, our results revealed that the effectiveness of the model to induce chronic bronchitis is mainly characterized by increased number of neutrophils and lymphocytes in BAL, followed by increased levels of proinflammatory cytokines (IL-1β, IL-6, CXCL1, IL-17, and TNF-α)." (PMID 29326759, 2017).
chronic lung infections (3 papers, 2021 to 2024). "Biofilms are common in both acute and chronic lung infections, inducing an inflammatory response marked by IL-1β and TNF-α39." (PMID 39366990, 2024).
chronic recurrent multifocal osteomyelitis (3 papers, 2014 to 2024). "Previous studies have found that IL-1β secretion and mRNA expression levels of key inflammasome components, namely apoptosis-associated speck-like protein containing a CARD and Caspase-1, are abnormally increased in patients with chronic recurrent multifocal osteomyelitis." (PMID 38287380, 2024). "Although the etiology of chronic non-bacterial osteomyelitis is still unknown, deficiency of IL-1β receptor antagonist and neonatal-onset multisystem inflammatory disease are caused by mutations in the IL1RN and NLRP3 genes, respectively, and result in over-activation of the IL-1β pathway." (PMID 24973754, 2014).
coccidioidomycosis (3 papers, 2023 to 2025). A fungal infection caused by Coccidioides immitis. "In response to Coccidioides infection, Spp1+ macrophages express high levels of pro-inflammatory (Nos2, Tgfb1, Il1β, and Il6) and fibrotic/wound healing associated genes (Inhba, Spp1, Arg1, Pdgfb, and Fn1)." (PMID 40704794, 2025). "In patients with pulmonary coccidioidomycosis, several cytokines were increased in high concentrations, including granulocyte-macrophage colony-stimulating factor (GM-CSF), interleukin-1β (IL-1β), interferon gamma (IFN-γ), IL-2, IL-13, and tumor necrosis factor alpha (TNF-α)." (PMID 37233224, 2023).
coronary stenosis (3 papers, 2019 to 2022). Narrowing of the coronary artery lumen diameter. "Plasma NGAL levels were positively related with MMP-9 and IL-1β levels and severity of coronary stenosis." (PMID 31387110, 2019). "The correlation analysis of SAH, IL-1β, Hcy, TNF-α, BDNF and the number of coronary artery stenosis was conducted by Kendall’s tau-b correlation, respectively." (PMID 35282820, 2022). "SAH, IL-1β, Hcy, TNF-α and BDNF in serum of patients with CHD can be used as effective biological indicators to monitor the degree of CHD and severity of coronary stenosis." (PMID 35282820, 2022). "NGAL had a better ability to discriminate severe coronary stenosis than MMP-9, IL-1β, and hs-CRP." (PMID 31387110, 2019). "NGAL had a better ability to discriminate severe coronary stenosis than MMP-9, IL-1β, or hs-CRP." (PMID 31387110, 2019).
cystic kidneys (3 papers, 2021 to 2022). "This was associated with an increased mRNA expression of Il1b, Tnf, Mcp1, Fn1, and Col1a2 genes in the cystic kidneys of Pkd1-miR Tg mice." (PMID 35955634, 2022).
diabetic macular edema (3 papers, 2015 to 2025). "Our results suggest that high levels of IL-1β, IL-6, and MCP-1 (proinflammatory and proangiogenic) and low levels of IL-10 (anti-inflammatory and anti-angiogenic) are involved in the pathogenesis of diabetic macular edema." (PMID 25923230, 2015).
Duchenne muscular dystrophy (3 papers, 2017 to 2021). Duchenne muscular dystrophy (DMD) is a neuromuscular disease characterized by rapidly progressive muscle weakness and wasting due to degeneration of skeletal, smooth and cardiac muscle. "IL-1β has also been implicated in muscle wasting disorders such as cancer cachexia, dysferlinopathy and Duchenne muscular dystrophy." (PMID 35047502, 2021).
dysentery (3 papers, 2008 to 2024). Acute inflammation of the intestine associated with infectious diarrhea of various etiologies, generally acquired by eating contaminated food containing toxins, biological derived from bacteria or other microorganisms. "IL-1β is known to cause neutrophilia and increased levels of circulating neutrophils were observed in these animals during dysentery and an increased neutrophil counts has been seen in colon lesions in pigs with dysentery." (PMID 18700003, 2008). "Blood was sampled before inoculation and repeatedly during acute dysentery and recovery periods and cytokine levels of IL-1β, IL-6, Il-10, TNF-α and IFN-γ were measured by ELISA." (PMID 18700003, 2008). "B. hyodysenteriae inoculation induced production of systemic levels of IL-1β during the dysentery period and increased levels of IL-10 coincided with recovery from dysentery." (PMID 18700003, 2008). "The pro-inflammatory cytokine IL-1β was increased in all clinically ill animals on the first day of the dysentery period (Figure." (PMID 18700003, 2008). "IL-1β was increased at the beginning of the dysentery period and coincided with the appearance of Serum amyloid A and clinical signs of disease." (PMID 18700003, 2008). "The aim of the present study was therefore to induce dysentery experimentally in pigs and to monitor the development of some immunoregulatory cytokines (IL-1β, IL-6, Il-10, TNF-α and IFN-γ) in blood collected at various stages of the disease." (PMID 18700003, 2008). "In the present study the levels of SAA in most animals accordingly rose 30- to 60-fold after the appearance of IL-1β and coincided with clinical signs of dysentery." (PMID 18700003, 2008). "In conclusion, increased levels of the pro-inflammatory cytokine IL-1β and SAA were detected during the period with dysentery, whereas an increase in IL-10 was seen during the recovery period." (PMID 18700003, 2008). "Increased levels of GM-CSF and reduced production of TNF-β, IL-1β, IL-17A, IL-16, IL-4, and IL-10 were distinct responses observed in Shigella-infected children with dysenteric diarrhea compared to Shigella without dysentery." (PMID 35924851, 2022). "The presence of IL-1β, IL-4, IL-16, and tumor necrosis factor beta (TNF-β) was associated with the absence of dysentery." (PMID 35924851, 2022). "Children with dysenteric Shigella exhibited significantly lower levels of TNF-β, IL-1β, and IL-17A but higher levels of GM-CSF than those without dysentery after adjustment for age and sex (blue circles)." (PMID 35924851, 2022). "Comparison of the response ratios of cytokines that were significantly different between children with and without dysentery confirmed that dysenteric Shigella was associated with >4-fold-higher levels of GM-CSF and reduced production of TNF-β, IL-1β, IL-16, and IL-4." (PMID 35924851, 2022).
Dysmenorrhea (3 papers, 2017 to 2025). Pain during menstruation that interferes with daily activities. "SFZYD has also been shown to effectively treat dysmenorrhea, a primary symptom of blood stasis, by regulating the expression of inflammatory cytokines, such as IL-1β, TNF-α, IL-10, IL-2 and IL-12, in a rat model." (PMID 28570676, 2017).
Ebola (3 papers, 2011 to 2021). "Similar cytokine patterns observed in our study in CCHF and HFRS patients, were seen also in patients with Ebola virus disease (EVD) where elevated levels of IL-1β, IL-1RA, IL-6, IL-8, IL-15, MIP-1α, MIP-1β, MCP-1, MCP-3, IP-10 and eotaxin were associated with fatal outcome." (PMID 31357521, 2019).
endocarditis (3 papers, 2018 to 2023). Inflammation of the endocardium. "In an experimental setup, HBO2 treatment has previously been demonstrated to downregulate IL-1β production, both in a model of zymosan-induced multi-organ failure, in a model of LPS-induced IL-1β production in human blood-derived monocyte-macrophages, and in a rat model of endocarditis." (PMID 37946314, 2023). "In contrast to Dufour’s conclusions that phage therapy did not induce an inflammatory response, phage therapy for endocarditis in rats induced by P. aeruginosa showed that phage therapy, but not ciprofloxacin, correlated with significantly increased plasma levels of IL-1β and IL-6." (PMID 34209836, 2021).
Ewing sarcoma (3 papers, 2016 to 2025). A small round cell tumor that lacks morphologic, immunohistochemical, and electron microscopic evidence of neuroectodermal differentiation. "In Ewing sarcoma, there were 21 significant relationships, including IL-4/IL-1β (r2 = 0.55, p = 0.00048), IL-4/IL-8 (r2 = 0.68, p = 0.0000047), CXCL14/IL-15 (r2 = 0.61, p = 0.00013), and CXCL5/CXCL12 (r2 = 0.64, p = 0.000030)." (PMID 41008853, 2025). "In studies on Ewing Sarcoma, the activation of CD99 in macrophages was shown to induce the secretion of characteristic chemokines such as IL1β, IL6, TNFα, and markers CD80 and CD86 by M1 macrophages." (PMID 41000385, 2025). "In contrast, high IL-1β did not predict worse EFS in patients with Ewing sarcoma (p = 0.36)." (PMID 41008853, 2025).
focal epilepsy (3 papers, 2014 to 2024). A seizure caused by a localized disorder. "Based on our research, many observational studies show that people with focal epilepsy have elevated levels of IL-1β." (PMID 39259090, 2024). "Additionally, IL-1β could promptly reduce the threshold of focal ictal events and enhance the likelihood that targeting these signaling pathways could prove an efficient therapeutic approach in preventing focal epilepsy." (PMID 39259090, 2024). "The purpose of the present study was to investigate the role of interleukin-1β (IL-1β) and high mobility group B1 (HMGB1) in the generation of seizure-like discharges using two models of focal epilepsy in a rat entorhinal cortex slice preparation." (PMID 24936172, 2014). "Specifically, focal epilepsy onset may induce increases in cytokines such as IL-7, IL-1Ra, IL-10, TNF-α, IFN-γ, and IL-1β, whereas inconsistent cytokine levels, including IL-5 and IL-1ra, may influence variations in focal epilepsy risk." (PMID 39259090, 2024).
folate deficiency (3 papers, 2019 to 2025). A nutritional condition produced by a deficiency of FOLIC ACID in the diet. "Folate deficiency may exert pro-inflammatory signaling by enhancing the monocyte–macrophage system, and the production of the inflammatory mediators, IL1β, IL6, TNFα, and MCP1, and monocytes were significantly increased when folate deficiency." (PMID 40740648, 2025). "It has been reported that folate deficiency might enhance the expression of the inflammatory mediators including IL-1β, IL-6 and TNF-α, independent of the concentration of homocysteine." (PMID 31296192, 2019).
G6PD deficiency (3 papers, 2019 to 2023). An X-linked genetic condition caused by alterations in the gene G6PD that result in moderately to severely decreased activity levels of the enzyme glucose-6-phosphate dehydrogenase. "Peripheral mononuclear cells produce lower levels of proinflammatory cytokines, IL-6 and IL-1β, under G6PD deficiency." (PMID 38049886, 2023). "Previous studies have shown that peripheral blood mononuclear cells from human subjects with G6PD-deficiency exhibit reduced secretion of inflammatory cytokines such as TNFα and IL-1β." (PMID 31805953, 2019). "To further understand the role of cytokines in the context of G6pd deficiency, we measured the expression of TNF-α, IFN-γ, IL-1β, IL-6, IL-12, TGF-β and IL-10 along with cytokine levels in serum and mRNA expression in spleen." (PMID 34456927, 2021).
Gaucher disease (3 papers, 2013 to 2025). Gaucher disease (GD) is a lysosomal storage disorder encompassing three main forms (types 1, 2 and 3), a fetal form and a variant with cardiac involvement (Gaucher disease - ophthalmoplegia - cardiovascular calcification or Gaucher-like disease). "Although mechanistically this has been explored to a much lesser extent in LSDs, in Gaucher disease, the accumulation of glucosylceramide causes inhibition of autophagy and subsequent inflammasome activation and generation of IL-1β." (PMID 39791736, 2025). "The pathways of IL1b and IL6 may require additional or specific stimuli (e.g., acute damage or inflammasome activation) that are not always present in Gaucher disease, especially in the early stages." (PMID 39902270, 2025).